LRP5 (LDL receptor related protein 5)
Diseases named in the same sentence as LRP5 in open-access papers (continued):
Sharing a sentence is not in itself a finding about the gene and the disease.
kidney diseases (3 papers, 2021 to 2025). "Dysregulation of LRP5/6 not only contributes to kidney diseases but also plays a critical role in the pathogenesis of CKD complications." (PMID 34026761, 2021). "While plentiful excellent reviews on Wnt signaling in human diseases, particularly the kidney disorders, have been published, relatively less is reported on the regulation and divergent functions of LRP5 and LRP6." (PMID 34026761, 2021). "In this study, we systematically review the structure, regulation and function of LRP5 and LRP6 in the context of kidney diseases, with emphasis on their commonality and uniqueness in mediating Wnt signaling." (PMID 34026761, 2021). "In this review, we systematically discuss the similarity and divergence of LRP5 and LRP6 in mediating Wnt and other signaling in the context of kidney diseases." (PMID 34026761, 2021). "Although LRP5 and LRP6 are co-receptors in canonical Wnt pathway, their exact role in kidney disease is unclear." (PMID 34026761, 2021).
retinopathies (3 papers, 2021 to 2024). "Within the ocular context, LRP5 mutations have been connected to retinopathies, and it has been shown to have an important role in vascular development in the retina." (PMID 39546296, 2024).
adenocarcinoma (1 paper, 2022). A common cancer characterized by the presence of malignant glandular cells. "However, LRP5 preferred adenocarcinomas of digestive organs, including the pancreas, colon, esophagus and stomach." (PMID 35850748, 2022). "WNT7A and WNT10A may contribute to female reproductive system adenocarcinomas, while LRP5 prefer adenocarcinomas of digestive organs." (PMID 35850748, 2022).
skeletal dysplasia (1 paper, 2016). Any Mendelian diseases that affects growth and development of the skeleton. "Individuals with LRP5 HBM (∼prevalence 5/100,000) displayed a variable phenotype of skeletal dysplasia with increased trabecular BMD and cortical thickness on HRpQCT, and gynoid fat mass accumulation on DXA, compared with both non‐LRP5 HBM and controls." (PMID 26348019, 2016).
LRP5 also shares sentences with these, for which no sentence is quoted: type 2 diabetes mellitus (8 papers); retinopathy of prematurity (5); genetic disorders (4); Anxiety (2); autosomal dominant osteopetrosis type 2 (2); cardiovascular disease (2); osteonecrosis of (2); pycnodysostosis (2); sarcopenia (2); triple-negative breast carcinoma (2); alcohol dependence (1); Allergy (1); amblyopia (1); Anorexia (1); Apert syndrome (1); autism spectrum disorder (1); autoimmune disease (1); autosomal dominant type 1 osteopetrosis (1); autosomal recessive polycystic kidney disease (1); bronchial hyperreactivity (1); bronchopulmonary dysplasia (1); cataract (1); chronic lymphocytic leukemia (1); chronic obstructive pulmonary disease (1); cocaine dependence (1); cognitive disorder (1); colorectal adenocarcinoma (1); congenital blindness (1); cranial neuropathies (1); craniodiaphyseal dysplasia (1).
A further 65 diseases each share a sentence with LRP5 in 1 paper.